LINC01806 (long independently transcribed non-coding RNA 1806)
Gene: Long non-coding RNA gene on chromosome 2 (161,244,544 to 161,262,898, forward strand). Ensembl gene ENSG00000227403.
Diseases named in the same sentence as LINC01806 in open-access papers:
LINC01806 is named in the same sentence as 1 disease in open-access papers, as found by Europe PMC text mining. Sharing a sentence is not in itself a finding about the gene and the disease. The quoted sentences say what the papers report.
tumor (1 paper, 2022). "Functionally, LINC01806 knockdown impeded cell proliferation, migration, invasion, and stemness, along with tumor growth." (PMID 35599309, 2022). "Results indicated that the positivity of SOX2, Ki67 and Oct4 was reduced in tumor tissues with silenced LINC01806." (PMID 35599309, 2022). "Moreover, depletion of LINC01806 retarded tumor growth in vivo." (PMID 35599309, 2022). "Moreover, tumor weight was decreased on account of LINC01806 down-regulation." (PMID 35599309, 2022). "LINC01806 was identified to be an oncogene in NSCLC since its knockdown hindered oncogenic phenotypes in vitro and blocked tumor growth in vivo." (PMID 35599309, 2022).